CD4 (CD4 molecule)
Diseases named in the same sentence as CD4 in open-access papers (continued):
Sharing a sentence is not in itself a finding about the gene and the disease.
COVID-19 (continued). "Moreover, severe COVID-19 patients have higher frequencies of CD4+ T-cells lacking CD62L expression than non-severe patients, suggesting potential homing to lymph nodes or infected tissues." (PMID 39597661, 2024). "HIV viral load and CD4 count were not collected at the time of COVID-19 diagnosis." (PMID 39321175, 2024). "Thus, the significant increase in CD3+ and CD4+ T-cells observed does not exclude the presence of multisystem inflammatory syndrome or its forms in children with COVID-19 across different age groups." (PMID 38397914, 2024). "We first compared SARS-CoV-2-specific CD4+ T-cell responses in unvaccinated asymptomatic COVID-19 patients (those individuals who never develop any COVID-19 symptoms despite being infected with SARS-CoV-2) to unvaccinated symptomatic (those patients who developed severe to fatal COVID-19 symptoms)." (PMID 38605956, 2024). "Since CD4+ T lymphocytes orchestrate innate and adaptive immune response, infection of CD4+ T cells by SARS-CoV-2 could explain lymphocytopenia and dysregulated inflammatory response in severe COVID-19 patients." (PMID 37523305, 2023). "Significantly increased percentages of CXCR4-expressing CD74+ CD4+ T cells (mean: healthy 61.5%, mild 84.0%, severe 81.0%) and CXCR4 CD74+ CD8+ T cells (mean: healthy 54.2%, mild 78.4%, severe 71.7%) were observed in both groups of COVID-19 patients in comparison to healthy controls." (PMID 37946732, 2023). "We identified the cellular source for pro-inflammatory cytokine storm in COVID-19 acute necrotizing encephalopathy patients as primarily originating from three cell subtypes, a CD14+ monocyte subset (Mono_CD14), a proliferative CD8 T subset (CD8_Pro) and a CD4 memory T subset (CD4_Memory)." (PMID 37848421, 2023). "Indeed, we confirmed that COVID-19 patients display a drop in the percentage of CD3+, CD4+ and CD8+ T cells and monocytes, while indicating that the decrease frequency of cDCs and pDCs may suggest a limited activation of antiviral T and NK cell functions." (PMID 37063865, 2023). "Immunostaining of COVID-19 brains revealed extensive activation of both microglia and astrocytes, severe damage of the blood–brain barrier (BBB) and various degrees of perivascular infiltration by predominantly CD14+/CD16+/CD141+/CCR7+/CD11c+ monocytes and occasionally CD4+/CD8+ T lymphocytes." (PMID 36609561, 2023). "It was found that the population of CD4+ TEMRA cells was not altered in COVID-19 patients." (PMID 37766091, 2023). "Importantly, we observed significant, positive correlations between every HLA-DR T cell population (CD4, CD8, and total) and every OX40+PD-1- T cell population (CD4, CD8, and total), highlighting the importance of T-cell activation biomarkers in monitoring COVID-19 patients." (PMID 38035104, 2023). "We found that severe COVID-19 patients had greater frequencies of CD4+ T cells expressing CD62L compared to non-severe COVID-19 patients (p=0.01), and recovered patients had greater frequencies of these cells compared to non-severe patients (p=0.02) and healthy controls (p=0.04)." (PMID 36817450, 2023). "CD4+ and CD8+ T cells could be activated by certain antigens in patients with COVID-19." (PMID 36768914, 2023). "Recent research on the immune mechanisms in COVID-19 refer to the initiation of infection by SARS-CoV-2 accompanied by cellular immune responses, including specifically poly-functional CD4+ and CD8+ T cell responses, which may become chronic along with immune inflammation." (PMID 36793739, 2023). "Supporting the hypothesis that regular access to care may increase vaccine uptake, we found that PWH who had not had a recently measured CD4 count or HIV VL over the study period were also less likely to receive any COVID-19 vaccination." (PMID 37996521, 2023).
COVID-19 (continued). "Reduced peripheral lymphocyte counts and, less frequently, decreased CD4+ counts have been linked to false-negative IGRA results in patients with tuberculosis and indeterminate QuantiFERON-TB Gold Plus assay results in COVID-19 patients." (PMID 37855635, 2023). "Two independent research groups observed that SARS-CoV-2 memory B cells, CD8+ T cells, and CD4+ T cells remained measurable for more than 6 months after infection, whereas antibodies against SARS-CoV-2 spike and RBD waned gradually 8 months after COVID-19 onset." (PMID 38140169, 2023). "Interestingly, we found higher CD3+CD4+CD25+FOXP3+CD39+ T cell frequency in unstimulated conditions in Mild Recovered volunteers who had not experienced musculoskeletal symptoms (arthralgia and myalgia) during acute COVID-19." (PMID 36969257, 2023). "Additionally, Cell Atlas analysis revealed that upregulated proteins were most significantly enriched for liver markers, while downregulated proteins were most significantly enriched for CD4+/CD8+ T cell markers, consistent with inadequate T cell response in the lungs of severe COVID-19 cases." (PMID 37942334, 2023). "We quantified CD4+ and CD8+ T-cells reactive to overlapping peptides spanning the ancestral SARS-CoV-2 spike protein in 40 older adults (median age 79) and 50 younger health care workers (median age 39), all COVID-19 naive, using an activation-induced marker assay." (PMID 38035132, 2023). "We found that the patients who had severe COVID-19 had low or absent cellular immune responses of CD4+IL-2+, CD4+IFN-γ+IL-2+, CD8+IFN-γ+IL-2+, and CD8+IFN-γ+IL-2+TNF-α+ after a booster dose, in line with the relevance of polyfunctional T cell responses against viruses." (PMID 37243116, 2023). "Therefore, we postulate that booster vaccination of inactivated COVID-19 vaccines would elicit similar non-spike-specific CD4+ and CD8+ T cell responses between wild-type and Omicron." (PMID 37114058, 2023). "Additionally, recovered COVID-19 patients had higher frequencies of CD4+ CD62L+ effector memory cells compared to non-severe COVID-19 patients (p=0.04)." (PMID 36817450, 2023). "The reported significant CD4+ and CD8+ T-cell response induced by the S1-RBD subunit (Ag1) and the S1 and S2 subunits of the S protein CD8+ T-cell epitopes (Ag2) after the first and second vaccine dose was similar to COVID-19 vaccinated healthy individuals reported in previous studies." (PMID 37515127, 2023). "Mild/moderate COVID-19-enriched Blautia obeum, Coprococcus catus and C. comes and severe/critical COVID-19-depleted Roseburia intestinalis showed a positive relationship with the number of lymphocytes, CD3+ T cells, CD4+ T cells and CD8+ T cells and lymphocyte proportion." (PMID 37205106, 2023). "However, modest CD4 and CD8 reductions have been documented in COVID-19 patients." (PMID 37465793, 2023). "The percentage of CD4+Th cells was significantly lower, while CD8+ Tc cells were significantly higher in the total Omicron COVID-19 patients group and the vaccinated Omicron COVID-19 patients group compared to the total mild SARS-CoV-2 patients (2020) group and uninfected control (p < 0.05 in each)." (PMID 37881339, 2023). "Several immunological changes connected to aging may also exacerbate COVID-19 pathogenesis such as altered IFN-γ signaling; neutrophilic infiltration; decreased CD4+ or CD8+ T cell, and naïve B cell levels; alveolar macrophage activation; and elevated release of pro-inflammatory cytokines." (PMID 36680215, 2023). "The higher CD4+ response in the vaccinated post-COVID-19 group compared to the uninfected group indicated that spike-specific T cell responses are dominated by CD4+ instead of CD8+ T cells, given that memory CD4+ T cells are primarily generated following infection." (PMID 37112825, 2023).
COVID-19 (continued). "Post-COVID-19 presented a lower percentage of Treg cells (p adj = 0.03) and altered markers of lymphocyte activation and exhaustion (lower CD28 expression in CD8+ T cells (p adj = 0.014), whereas CD4+T cells showed higher PD1 expression (p adj = 0.037)) compared with the control group." (PMID 37753077, 2023). "Whether CD4+ CTLs collaborate with DN3 B cells in tumor immunity remains undetermined, despite these observations having been consistently identified in the pathogenesis of IgG4-RD, systemic sclerosis, fibrosing mediastinitis, and COVID-19." (PMID 38077321, 2023). "There was a significant correlation between worst COVID-19 outcome on the 8-point scale and activated cTfh cells (P = 0.005) and between worst COVID-19 outcome on the 8-point scale and both CD38 and HLA-DR upregulation on CD4+ T cells (P = 0.008) and CD8+ T cells (P = 0.002)." (PMID 36862515, 2023). "COVID-19 patients showed high infiltration of plasma cells, CD4+ T cells memory activated, M0 macrophages, dendritic cells activated and neutrophils than normal samples, while normal patients showed high level of B cells memory, CD8+ T cells and CD4+ T cells memory resting than COVID-19 patients." (PMID 37606960, 2023). "Indeed, CD8 + T cells rather than CD4 + T cells were decreased in severe and critical COVID-19 compared with moderate status." (PMID 37488118, 2023). "Moreover, CD4 T cell (p = 0.047) level was higher in the COVID-19 vaccinated group than in the non-vaccinated group." (PMID 37679851, 2023). "Immunological studies among subjects with long COVID who had mild acute COVID-19 (no hospitalization and no respiratory disease) have demonstrated T cells exhaustion with reduced CD4+ and CD8+ effector memory cell numbers and elevated PD1 expression on central memory cells." (PMID 36831611, 2023). "To assess the cell type specificity of the epigenetic markers for CD3+, CD4+, and CD8+ T cells as well as total B, naïve, and memory B cells in nasal swabs we performed a joint data analysis of qPCR data of healthy donors and COVID-19 patients in comparison to blood." (PMID 36999021, 2023). "We extracted data from observational studies, and the factors included age, gender, CD4 T-cell count, HIV viral load, comorbidities, days after complete vaccination, and vaccine type and were evaluated with respect to the seroconversion rate in PLWH after COVID-19 vaccination." (PMID 37112701, 2023). "Within the reduced CD4+ T cell compartment, HD + COVID-19 patients had a tendency towards decreased frequencies of central memory (CM) CD4+ T cells and increased effector memory (EM) and terminally differentiated effector memory (TEMRA) CD4+ T cells compared to HC and uninfected HD patients." (PMID 36675231, 2023). "Hence, the COVID-19 vaccination should be recommended for PLWH regardless of their CD4 count and HIV viral load levels and possibly prioritized in vaccination rollouts." (PMID 36627582, 2023). "Since the CoV-ETH study group did not include severely ill or ICU patients, the role for CD4 T cells in individuals with severe COVID-19 outcomes could not be established." (PMID 37313411, 2023). "Thus, we assessed the impact of MDSCs on CD4 + CD25 + Foxp3 + T in HC and COVID-19 patients." (PMID 36581679, 2022). "However, a retrospective study including 275 patients with COVID-19 found no beneficial effects for Tα1 on the recovery of CD4+ and CD8+ T cell counts and viral clearance during COVID-19 convalescence." (PMID 36567402, 2022). "Another suggestion from Y. Wang and colleagues is that cross-reactive CD4+ and CD8+ T-cells lymphocytes contribute to SARS-CoV-2 infection resistance via the production of a virus-specific TCR recombination pattern as overlap indices of TCRB CDR3 amino acid sequences are higher in COVID-19 patients." (PMID 35955721, 2022).
COVID-19 (continued). "In addition, COVID-19 plasma exosomes failed to affect cytokine production in CD4+/CD45RO+ central memory T cells that were selected using a CD4+ central memory T cell isolation kit (Miltenyi)." (PMID 36526691, 2022). "However, the analysis of the CD3low populations revealed WT S-reactive CD4+ T cells with higher avidity among the COVID-19 cohort compared to the VBI patients, suggesting there is no vaccination advantage among the VBI cohort." (PMID 35145522, 2022). "Likewise, HLA-DR expression and the percentage of CD4+ T lymphocytes specific against Mtb were both similar between patients with COVID-19 and aTB compared to patients without COVID-19." (PMID 36090983, 2022). "A low avidity profile was also observed for SARS-CoV-2-specific T cells in non-exposed donors, suggesting that pre-expanded CD4 T-cell responses could accumulate during COVID-19 in the context of inflammation and be inefficient to clear the virus." (PMID 35529881, 2022). "However, regression analysis showed that only ALB, NLR, CD4/CD8 ratio, and eosinophil count were risk predictors for the viral shedding duration in patients with non-severe COVID-19." (PMID 36620263, 2022). "Moreover, patients with progressive COVID-19, who succumbed to infection, had increased ZBP1 expression in their immune cells, particularly NK cells, CD4+ memory and naïve T cells, effector memory CD8+ T cells and B memory and naïve cells, compared with patients with stable COVID-19." (PMID 35587515, 2022). "We next determined the effect of SARS-CoV-2 infection on CD4+ and CD8+ distribution among CD45+ cells; AT CD4 and CD8 T cells have antiviral properties, are involved in the metabolic regulation of AT52,57, and are severely reduced in the blood of patients with severe forms of COVID-19." (PMID 35661814, 2022). "Moreover, regression analysis showed that both NLR and CD4/CD8 ratios were associated with prolonged elimination of the virus, suggesting NLR and CD4/CD8 ratios as effective indicators of the viral shedding duration in patients with non-severe COVID-19." (PMID 36620263, 2022). "In this regard, alone or combined expression level of PD1 on CD4+ T-cells as well as the expression level of CD38 on CD8+ T-cells could be potential biomarkers in the prediction of disease severity and outcome in patients with COVID-19." (PMID 35655192, 2022). "While the CD4+ T cell responses towards spike protein-derived peptides are promising, the reduced antibody responses confirm that two and even three doses of mRNA vaccine may be insufficient to protect PLWH from COVID-19." (PMID 36532034, 2022). "Our results demonstrated that strong CD4+ T cell and weak CD8+ T cell responses were reactivated by inactivated vaccination in COVID-19 recovered individuals over one year from disease onset, which may be due to the role of helper T (Th) cells assisting with antibody production." (PMID 35979361, 2022). "The CD4+ T cell responses to the SARS-CoV-2 S or N proteins have been shown to correlate with the magnitude of the anti-SARS-CoV-2 neutralizing antibodies in recovered patients, a finding suggesting a potential role for the S protein in triggering a protective response to COVID-19." (PMID 35844575, 2022). "In conclusion, while the cellular immune response by CD4+ T cells is surprisingly comparable to the control group, the humoral response mediated by antibodies is reduced suggesting that PLWH might be less protected from COVID-19 by vaccination." (PMID 36532034, 2022). "We found strong positive correlation between lymphocytes counts and CD3+, CD4+, CD8+ T cells, and CD19+ B cells absolute counts, and strong negative correlation between the percentages of CD16+CD56+ NK cells and CD3+ T cells in both COVID-19 patients and the vaccinated individuals." (PMID 35898494, 2022). "Furthermore, CD4+ responses—not the antibody response—appear to be the best predictor of COVID-19 severity." (PMID 35746512, 2022).
COVID-19 (continued). "Transfusions of CD4+ and CD8+ T cells may prove very rewarding in clearing COVID-19." (PMID 35955740, 2022). "Increased COVID-19 severity and chronic HIV-1 infection are accompanied by high expression of T cell inhibitory receptors including programmed cell death-1 (PD-10) and T cell immunoglobulin mucin 3 (Tim-3) proteins, which contribute to the low CD4+ T cell counts and reduction of IFN-γ production." (PMID 36313221, 2022). "CD4 T-cell and total T-cell numbers in critical COVID-19 patients were significantly lower than those in severe patients (p < 0.0001), and CD8 T-cell numbers in critical COVID-19 patients were also markedly decreased compared to those in severe patients (p < 0.05)." (PMID 36403042, 2022). "Interestingly, both the CD4+ T and CD8+ T cells from multivalent COVID-19 inactivated vaccine-immunized mice could secrete more IFN-γ after viral stimulation." (PMID 35746564, 2022). "However, even if we could study a relatively low number of patients, we could define the polyfunctionality profile of CD4+ and CD8+ T cells during and after SARS-CoV-2 infection in patients experiencing different severities of COVID-19." (PMID 35887351, 2022). "However, conversely to antibody levels, the proliferative CD4+ T-cell response did not decrease significantly at the late time point in both post-COVID-19 and vaccinated subjects." (PMID 35744768, 2022). "However, this study did not take into account the impact of CD4+ T-cell count or the ART therapy in the prevention of mortality from COVID-19." (PMID 35458478, 2022). "Thus, we have investigated whether in vitro stimulation of PBMCs from vaccinated individuals with a pool of peptides derived from the Spike protein resulted in activation of specific CD4+ and CD8+ T lymphocytes, as it was described in COVID-19 patients." (PMID 35359985, 2022). "Because the stimulation of P2X7R expressed by CD4+ T cells has shown to promote the differentiation of CD4+ T cells into TH17 and TH1 profiles, this might explain, at least in part, the promotion of the TH17 profile observed in children with COVID-19." (PMID 35663467, 2022). "Analyses were limited to availability of results from public health reporting of HIV-related laboratory tests reported to HIV surveillance; many people did not undergo viral load and CD4 testing upon admission, which limited the understanding of severe COVID-19 on these measures." (PMID 35613145, 2022). "Regarding another example of COVID-19 patients with anosmia/ageusia, elevated percentages of B-lymphocytes and immature B-lymphocytes but lower percentages of activated CD8+ T-lymphocytes, activated CD4+ T-lymphocytes, and monocytes were detected when compared to patients without anosmia/ageusia." (PMID 36366522, 2022). "Interestingly, clinical studies have reported a decrease in CD4+ and CD8+ T lymphocyte counts in COVID-19 patients, and, therefore, the effects of R848 could be recapitulating the lymphopenia observed in this disease." (PMID 34991643, 2022). "There was an inverse relationship between the proportion of CD45RO+ antigen-experienced cells and the frequency of SARS-CoV-2-specific CD4+ T cell responses per million CD4+ T cells in previously hospitalized subjects but not in subjects with a history of mild COVID-19 (non-hospitalized)." (PMID 35857584, 2022). "Also, in convalescent antibody-positive and -negative COVID-19 patients, a robust T-cell response was characterized by the presence of reactive CD4+CD154+CD137+ and CD154+CD137+ T-cells." (PMID 36389664, 2022). "We have found that recovery from severe COVID-19 leads to functional shift after the first 3 months post-infection, resulting in polarization towards an exhausted/senescent state of CD4+ and CD8+ T cells and perturbations in CD4+ Treg subsets, clearly visible at 6 months after COVID-19." (PMID 35757700, 2022).